GFAP (glial fibrillary acidic protein)
Diseases named in the same sentence as GFAP in open-access papers (continued):
Sharing a sentence is not in itself a finding about the gene and the disease.
neurodegenerative disease (continued). "This is proposed to be due to a common underlying mechanism of neuroinflammation, and thus suggests CSF GFAP is not suitable for distinguishing between neurodegenerative diseases." (PMID 34267329, 2021). "Studies of glial fibrillary acidic protein (GFAP), an astrocytic damage marker, may help advance our understanding of different neurodegenerative diseases." (PMID 34893073, 2021). "This may contribute to higher baseline plasma GFAP levels in older adults, even without neurodegenerative disease." (PMID 40690136, 2025). "Higher expression levels of GFAP have been shown in post-mortem MSA brain tissue compared to PD and healthy controls (HC), while first data also show a detectable upregulation of GFAP in CSF and plasma in multiple neurodegenerative diseases, including atypical parkinsonian syndromes." (PMID 39254698, 2024). "Based on these findings, it would seem that GFAP responds to acute neuronal injury; however, in a chronic neurodegenerative disease, and unlike NfL, plasma GFAP may principally (but not exclusively) reflect Aβ pathology." (PMID 34661615, 2021). "While there was no overall relationship between neurodegenerative disease biomarkers and myelin content after accounting for age and other demographic factors, we found that age appears to modify the relationship between myelin content and these biomarkers, particularly for pTau181, NfL, and GFAP." (PMID 36762407, 2023). "However, given that serum GFAP levels may be elevated in patients with neurodegenerative diseases or traumatic brain injury and no cut-offs have been defined to differentiate these pathologies, the utility of GFAP is currently limited." (PMID 34885083, 2021). "In contrast to that reported in other neurodegenerative diseases (such as AD), the analysis of confocal images did not reveal signs of astrocytes reactivity in ALS retina, evaluated as the area covered by the GFAP signal." (PMID 37009460, 2023). "The lack of correlation between YKL-40 and GFAP together with the positive correlation between tau and GFAP (r = 0.651) in our study also may indicate that YKL-40 expression is independent of astrocyte activation in neurodegenerative disease." (PMID 28599675, 2017).
neurological diseases (147 papers, 2010 to 2026). "GFAP is a frequently used astrocyte-specific marker protein, and its upregulation plays an active role in the pathological processes of many neurological diseases associated with inflammation." (PMID 41329536, 2025). "Elevated GFAP levels in the blood have been associated with various neurological disorders, including Alzheimer’s disease (AD), multiple sclerosis (MS), and TBI." (PMID 39594187, 2024). "These genes include MOBP (an oligodendroctye and white matter marker), PCP4 (associated with L5 and L6) and GFAP (associated with astrocytes and many neurological disorders)." (PMID 35380614, 2022). "Several neurological diseases are associated with reactive astrogliosis and GFAP overexpression, often correlating with the severity of the impairment." (PMID 36009513, 2022). "Astrocyte-secreted GFAP is regarded as a marker of astrocytosis in neurodegeneration associated with neurological disorders." (PMID 35447931, 2022). "GFAP is associated with a range of neurological disorders, including central nervous system (CNS) immune inflammatory diseases, congenital diseases, and traumatic disorders." (PMID 33569363, 2020). "It’s direct role in neurological diseases is not well understood and somewhat controversial depending on the disease in question, but increased GFAP staining is associated with gliosis and neuroinflammation." (PMID 28223982, 2017). "AxD is a neurological disease with astrocyte dysfunction and is caused by genetic mutation of the GFAP gene." (PMID 27396343, 2016). "While the full extent of citrullinated GFAP’s effects remains unclear, it has been implicated in autoimmune responses related to neurological diseases, interference with GFAP polymerisation, and disease-specific variations in citrullination levels." (PMID 40690136, 2025). "The diagnostic value of GFAP varies across biological fluids and neurological diseases." (PMID 39289040, 2025). "Here, we review how Tau, GFAP, and NfL biomarkers are detected in CSF and blood as crucial diagnostic tools, as well as the levels of these biomarkers used for differentiating a range of neurological diseases and monitoring disease progression." (PMID 38928000, 2024). "Serum GFAP level is associated with the severity of neurological diseases like head injury (correlations with the severity of neuroimaging brain injury, as well as with the Glasgow Coma Scale), as well as with the progression of multiple sclerosis (clinical and neuroradiological)." (PMID 39062788, 2024). "Increased GFAP has been associated with AD and other neurological diseases in previous studies." (PMID 38257772, 2023). "We further performed next generation sequencing of customized panel, targeting 95 genes associated neurologic disorders by target capture method, resulting in known pathogenic heterozygous p.Arg70Trp variant (NM_002055.4:c.208C > T) in GFAP gene, confirmed by Sanger sequencing method." (PMID 31952467, 2020). "GFAP was similarly elevated—reflecting astrocytic activation—but its discriminative performance is limited by its poor specificity, since many other neurological disorders also raise GFAP levels." (PMID 41574640, 2026). "GFAP is expressed in mature astrocytes, and acts as a well-established marker of astrocyte injury and activation in several neurological diseases." (PMID 41539185, 2026). "GFAP, an essential protein filament found in astrocytes, plays a critical role in synaptic function and has been widely researched in many neurological disorders affecting the brain and spinal cord." (PMID 40219863, 2025). "GFAP, a marker for astrocytes, is upregulated in reactive astrocytes during neurological disorders, reflecting reactive astrogliosis." (PMID 40309788, 2025). "The advent of ultra‐sensitive methods for measuring low‐abundant proteins has significantly enhanced our understanding of GFAP levels in the serum or plasma of patients with diverse neurological diseases." (PMID 39289040, 2025).
neurological diseases (continued). "By taking an example of other successful biomarkers developed for various neurological diseases, we can harness the GFAP proteoform diversity to develop more accurate and disease‐specific biomarkers (see Concluding remarks)." (PMID 39289040, 2025). "Other relevant limitations for diagnostic accuracy include possible confounders impacting serum NfL and GFAP levels, such as previous neurologic disease or the presence of brain metastasis." (PMID 39831665, 2025). "Both NfL and GFAP have broad relevance across multiple neurological disorders as blood-based biomarkers." (PMID 40637865, 2025). "Glial fibrillary acidic protein (GFAP) has been shown to be a reliable biomarker for detecting neurological disorders." (PMID 40943059, 2025). "Further, we found NfL and GFAP to relate to outcome 10–15 years trauma, adjusted for age and neurological disease." (PMID 38769253, 2024). "After adjustments for age and neurological diseases, a relative increase in NfL and GFAP of 50% significantly increased the odds of a GOS 1–3 outcome 10–15 years after trauma (OR 2.04, p = 0.035, and OR 1.60, p = 0.040, respectively)." (PMID 38769253, 2024). "Toll-like-receptor 4 (TLR4) is the main receptor for LPS, which mediates pro-inflammatory signaling in various neurological disorders and glial fibrillary acidic protein (GFAP) is a common marker for astrocyte activation." (PMID 39337602, 2024). "New highly sensitive assays, such as single-molecule arrays (SIMOAs), have been developed to measure GFAP levels in blood from healthy individuals and those with various neurological diseases." (PMID 39594187, 2024). "Researchers reviewed the evidence regarding the utility of serum GFAP as a biomarker in neurological diseases and they believed that clinical use of GFAP measurements had the potential to contribute to accelerated diagnosis and improved prognostication." (PMID 38902461, 2024). "Particularly, there is growing interest in a novel blood biomarker known as glial fibrillary acidic protein (GFAP) in the field of neurological diseases." (PMID 38711771, 2024). "Neurofilament light-chain protein (NfL) and glial fibrillary acidic protein (GFAP) levels in serum and cerebrospinal fluid (CSF) have emerged as biomarkers for neurological diseases." (PMID 38581544, 2024). "Recent studies indicated that GFAP is promising biomarker for several neurological diseases other than CAA." (PMID 38654326, 2024). "Here we elaborated the implications of GFAP in the pathological processes of diverse neurological diseases, aiming at exploring the on potential therapeutic strategies from the perspective of GFAP." (PMID 38216970, 2024). "Continued investigation into GFAP will be essential for advancing our understanding and management of traumatic brain injuries and related neurological disorders." (PMID 39796043, 2024). "Glial fibrillary acidic protein (GFAP), a structural astrocytic protein that differs according to the stage of the cell proliferation cycle, plays a notable role in multiple neurological disorders." (PMID 39062515, 2024). "GFAP levels measured in blood is increasingly recognized as a promising biomarker in neurological diseases, including acute stroke." (PMID 39777311, 2024). "Multiple studies have shown the importance of blood-based biomarkers indicating axonal damage (serum neurofilament light chains [sNfL]) or astroglia activation (serum glial fibrillary acidic protein [sGFAP]) for monitoring different neurological diseases." (PMID 39063050, 2024). "GFAP expression is tightly regulated during brain development and varies across different neurological diseases." (PMID 39796043, 2024). "In neurological disorders involving astrocytic activation, astrocyte disintegration leads to the release of GFAP into the bloodstream, elevating plasma levels of GFAP." (PMID 37932720, 2023).
neurological diseases (continued). "Blood GFAP levels increase not only in NMOSD but in various neurological diseases, thus the specificity of GFAP as an NMOSD biomarker should be discussed." (PMID 35370870, 2022). "These pilot results encourage multicenter longitudinal studies to further investigate serum GFAP as a complementary tool to better understand and monitor neurological disease progression in ETPKU." (PMID 36247773, 2022). "As one of the brain-specific cytoskeletal proteins, GFAP (glial fibrillary acidic protein) plays an important role in maintaining the structural and functional integrity and is regarded as an essential biomarker for neurological disorders." (PMID 35365622, 2022). "These pilot results motivate multicenter longitudinal studies to further investigate blood-based biomarkers such as GFAP and NfL as a complementary tool to better understand and monitor neurological disease progression in ETPKU for the following three reasons." (PMID 36247773, 2022). "Glialfibrillaryacidic protein (GFAP) is a discriminative bloodbiomarker for many neurological diseases, such as traumatic braininjury." (PMID 34908400, 2022). "No autopsy studies have been performed on any of these although there are several brain biopsy studies of patients with glial fibrillary acidic protein (GFAP)-autoantibodies and neurological disease." (PMID 35204019, 2022). "Sevoflurane can induce expression of GFAP and activation of ACs and, resulting in neurological disorders in mice." (PMID 36037402, 2022). "Serum samples were measured for several proteins known to be elevated in various forms of neurological disease or injury: neurofilament-light (NfL), glial fibrillary acidic protein (GFAP), tau and ubiquitin c-terminal hydrolase L1(UCHL1) 5–7." (PMID 36114333, 2022). "Both, CHI3L1 and GFAP, are described as markers of astrocyte activation or damage in MS as well as other neurological diseases." (PMID 36142860, 2022). "GFAP BDPs between 38 and 44 kDa are a result of pathological activation of the calcium-dependent protease calpain and serve as biomarker for other neurological diseases such as traumatic brain injury." (PMID 36434021, 2022). "That said, prior work has reported low to very low levels of blood-based GFAP in patients with a variety of neurological diseases, despite the presence of neurological symptoms." (PMID 36153327, 2022). "GFAP, a marker of intermediate filaments in astrocytes that become hypertrophic in response to insult, has been shown to be increased in a number of neurological diseases, including NF1." (PMID 32074109, 2020). "The activation of astrocytes, characterized by cellular hypertrophy and an increase in glial fibrillary acidic protein (GFAP) expression, is a histopathological hallmark of diverse neurological disorders, including AD." (PMID 32331524, 2020). "Chromogranin A, synaptophysin, S-100B protein and GFAP are well known neuroendocrine markers involved in cancer and in neurological diseases." (PMID 31263455, 2019). "Although astrocytes have two roles in the pathological mechanisms of neurological diseases, our finding of a reduction in the number of GFAP(+) cells can be interpreted as a reduction of astrogliosis." (PMID 31024439, 2019). "GFAP expression is not limited to the central nervous system and also found in the peripheral nervous system in specific neurological diseases including ALS." (PMID 30487774, 2018). "Increased levels of GFAP protein has been identified in the blood samples of patients suffering from neurological diseases, such as Parkinson's disease, intracerebral hemorrhage, traumatic spinal cord injury, and multiple sclerosis." (PMID 30487774, 2018). "In an exploratory study of a broad spectrum of neurological diseases, GFAP levels were very low in most patients." (PMID 29255443, 2017).
neurological diseases (continued). "In this respect, overexpression of several intermediate filaments including glial fibrillary acidic protein, peripherin or neurofilaments in mice has been shown to be toxic, leading to neurological disorders affecting the respective organs." (PMID 25617501, 2015). "Apart from a considerable number of acute stroke patients, whose GFAP blood levels are reported in the literature, only little is known about GFAP in patients with other neurological diseases." (PMID 23626774, 2013). "This explorative study is the first to provide plasma levels of the brain specific astroglial protein GFAP in patients with a broad spectrum of neurological diseases." (PMID 23626774, 2013). "Here, we evaluated a finger-prick blood collection approach for remote quantification of neurofilament light (NfL), a candidate blood-based biomarker evident in various neurological disorders, and other exploratory markers of neuronal injury and neuroinflammation (GFAP, tau)." (PMID 40637865, 2025). "There have been continuous studies reporting neuronal GFAP expression during the progression of neurological diseases; for example, distinct GFAP splice forms expressed in pyramidal neurons of the hippocampus were identified in the brain tissues of AD patients." (PMID 40175324, 2025). "Glial fibrillary acidic protein (GFAP) is a well‐established biomarker of reactive astrogliosis in the central nervous system because of its elevated levels following brain injury and various neurological disorders." (PMID 39289040, 2025). "Recently, advancements in the treatment of neurological diseases have highlighted the increasing importance of biomarkers, creating a demand for accurate and simple measurement systems for GFAP levels, which are essential for both research and clinical applications." (PMID 39594187, 2024). "As a marker protein of astrocytes, GFAP may exert a variety of physiological effects in neurological diseases." (PMID 38216970, 2024). "Therefore, pre-clinical and clinical studies are warranted to understand the role of GFAP in neurological diseases." (PMID 38216970, 2024). "Similarly to GFAP, another plasma biomarker that is altered across several neurological disorders is neurofilament light chain (NfL)." (PMID 38623387, 2024). "The biofluid-based biomarker Glial Fibrillary Acidic Protein (GFAP) and its breakdown products (GFAP-BDPs) may be useful for diagnosing neurological diseases such as PD." (PMID 37108480, 2023). "GFAP is an intermediate filament protein of astrocytes, considered a specific marker of astrocyte activation and/or injury that usually occur following exposure to neurotoxic elements or other neurologic disorders." (PMID 36745244, 2023). "Even though one might have expected a better detection of markers of axonal damage and glial activation in the CSF than in the serum, a high sensitivity of serum markers to disease severity was indeed shown in various neurological diseases for NfL and GFAP." (PMID 36009416, 2022). "In neurological disorders, the astrocytes undergo significant morphological and molecular phenotypic changes, the most widely characterized of which are cellular hypertrophy and upregulation of the intermediate filament protein GFAP." (PMID 34873637, 2022). "These markers include the elevation of blood-derived molecules in the CSF such as total immunoglobulins, proteins, or albumin, but also more specific markers of neurological disease such as glial fibrillary acidic protein (GFAP), neuron-specific enolase (NSE), or S100 beta proteins." (PMID 35887567, 2022). "In the paper, the authors demonstrated that the GFAP gene was over-expression in GBM and that GFAP could be considered as a biomarker of astrocytic pathology in neurological diseases." (PMID 34149811, 2021). "In addition, GFAP was also increased after mild traumatic brain injuries, suggesting the potential application of blood GFAP in neurological diseases." (PMID 34867769, 2021).